SLC61A1 (solute carrier family 61 member 1)
Description:
Mediates high-affinity intracellular uptake of the rare oligo-element molybdenum.
Synonyms: hsMOT2; MFSD5; MGC11308
Tractability: Antibody: UniProt places it where antibodies can reach, with high confidence; UniProt predicts a signal peptide or a membrane-spanning region; its Gene Ontology location is reachable by antibodies, with medium confidence. PROTAC: ubiquitination databases record sites on it.
Gene: Protein-coding gene on chromosome 12 (53,251,251 to 53,254,406, forward strand). Ensembl gene ENSG00000182544.
Subcellular location: Cell membrane
Gene Ontology:
Molecular function: molybdate ion transmembrane transporter activity; protein binding
Biological process: molybdate ion transport
Cellular component: membrane; plasma membrane
Genetic constraint (gnomAD): Loss-of-function variants: 19 observed, 28.55 expected, observed/expected ratio (o/e) 0.67, 90% interval 0.46 to 0.98. The upper end of that interval is the gene's LOEUF score, 0.98, which puts it in group 4 of 6, group 1 being the genes least tolerant of losing a copy. Missense variants: 496 observed, 583.16 expected, observed/expected ratio (o/e) 0.85, 90% interval 0.79 to 0.92. Synonymous variants: 236 observed, 247.5 expected, observed/expected ratio (o/e) 0.95, 90% interval 0.86 to 1.06.
Homologues: Orthologues: chimpanzee MFSD5 (99% identical), macaque MFSD5 (99% identical), guinea pig MFSD5 (98% identical), rabbit MFSD5 (97% identical), pig MFSD5 (97% identical), dog MFSD5 (97% identical), mouse Mfsd5 (96% identical), rat Mfsd5 (96% identical), tropical clawed frog mfsd5 (66% identical), zebrafish mfsd5 (61% identical), Caenorhabditis elegans mfsd-8 (9% identical), Caenorhabditis elegans F58G11.4 (9% identical), and 6 more. Paralogues in human: SLC75A1 (16% identical), SLC71A1 (15% identical), SLC71A2 (14% identical), SLC67A2 (14% identical), MFSD1 (12% identical), MFSD8 (12% identical).
Diseases named in the same sentence as SLC61A1 in open-access papers:
SLC61A1 is named in the same sentence as 2 diseases in open-access papers, as found by Europe PMC text mining. Sharing a sentence is not in itself a finding about the gene and the disease. The quoted sentences say what the papers report.
diabetes (1 paper, 2020). "In addition, Mfsd1 and Mfsd3 (presently called Slc33a2), Mfsd5 (now under the name of Slc61a1) and Mfsd11, Mfsd14a and Mfsd14b, and Unc93a are all affected by energy availability mice in vivo and Mfsd9 is linked to diabetes." (PMID 32733888, 2020).
SLC61A1 also shares sentences with these, for which no sentence is quoted: tumor (1 paper).